KRAS (KRas proto-oncogene, GTPase)
Diseases named in the same sentence as KRAS in open-access papers (continued):
Sharing a sentence is not in itself a finding about the gene and the disease.
cancer (continued). "NSCLC is also the first cancer for which the use of a drug directed against a specific KRAS mutation, p.G12C, has been approved." (PMID 36010306, 2022). "The KRAS-variant was the first microRNA binding site mutation discovered in cancer, and is a functional germline mutation in the 3′ untranslated region." (PMID 35562926, 2022). "Thousands of DNA mutations (e.g., KRAS) have been found in cancers and dozens of RNAs (e.g., PANDAR) alter their gene expression during cancer development, but none of these provides consensus, even in a given cancer type." (PMID 35053515, 2022). "Lastly, we applied Onepot-Seq to profile dose-dependent responses of cancer cell lines to the KRAS(G12C) inhibitor AMG-510 and observed G12C mutation-specific responses of KRAS-dependent genes at single-cell resolution." (PMID 35953080, 2022). "Accordingly, mutations in MUC16 (CA125) were selected for in EGFR-mut and KRAS-mut cancers while only mutations in MUC17 were selected in NEK." (PMID 36612014, 2022). "23% of adult pan-cancer samples had KRAS alterations; 88% were mutations, most commonly G12D/G12V/G12C/G13D/G12R, and prevalence was similar in liquid biopsies." (PMID 36494601, 2022). "We recently performed transcriptome and proteome profiling of human lung epithelial cells ectopically expressing oncogenic KRAS and another cancer-associated Ras GTPase, RIT1." (PMID 36522653, 2022). "KRAS is one of the most commonly mutated oncogenes in many cancers (for example, in pancreas and lung)." (PMID 35280777, 2022). "While KRAS-associated miRNAs have been widely studied in cancer, the role of KRAS-related lncRNAs in promoting cancer progression needs to be carefully examined." (PMID 34489556, 2022). "KRAS-related carcinogenic mutations are prevalent in human cancer, occurring in 17%–25% of all cancers." (PMID 36330448, 2022). "The MAPK paradox explained that anti-BRAF agents in KRAS-mutated cancers are contraindicated because of the activation of tumorigenesis by the binding to BRAF." (PMID 36012655, 2022). "Activation of the ERK pathway in tumors with KRAS mutations is involved also in cancer immune escape." (PMID 36358725, 2022). "In many cancers, KRAS mutation rate is high, such as 96% in pancreatic cancer, 52% in colorectal cancer and 32% in non-small cell lung cancer." (PMID 36189266, 2022). "The phase II portion of CodeBreaK100 explored sotorasib 960 mg once daily in cancers with a KRAS G12C mutation." (PMID 36284306, 2022). "The KRAS proto-oncogene is among the most frequently mutated genes in cancer, yet for 40 years it remained an elusive therapeutic target." (PMID 34990404, 2022). "Because these three cancers alone are responsible for the majority of KRAS mutations found in human cancer (77%), much of the current focus on KRAS-mutant cancer therapeutics is targeted against these cancers." (PMID 35045886, 2022). "Synthetic lethal drug screening reported that KRAS-mutated cancer cells seem vulnerable to PLK1 inhibition and depend more heavily on PLK1 activity for mitotic progression." (PMID 36142803, 2022). "The three mammalian RAS genes (HRAS, NRAS and KRAS) encode four proteins that play central roles in cancer biology." (PMID 36393833, 2022). "KRAS wild-type cancers had lower GALNT6 mRNA expression levels than KRAS mutated cancers, whereas BRAF mutated tumors had lower GALNT6 mRNA expression levels than BRAF wild-type tumors." (PMID 35692787, 2022). "This discovery provides a new theoretical basis for the study of targeted therapies for cancers with KRAS mutations." (PMID 36713456, 2022).
cancer (continued). "Altogether, our results revealed another mechanism that PDAC cells utilize to self-promote cancer dissemination through oncogenic KRas mutations and its downstream targets CCL15 and ROS in order to enhance cell migration and invasion." (PMID 35565279, 2022). "KRAS-mutated LUADs are a subgroup of cancers that are heterogeneous in their molecular background and clinical response to therapy." (PMID 35205778, 2022). "Mutations in the KRAS proto-oncogene are the most frequently observed genetic lesion in human cancer and are estimated to account for one million deaths every year worldwide." (PMID 35864332, 2022). "KRAS is one of the most frequently mutated oncogenes in all human malignancies and is seen in 1 in 7 of all human cancers." (PMID 36284306, 2022). "KRAS is a signal transducer protein that binds to GTP in the MAPK pathway; the mutation of KRAS has been discovered in a quarter of human cancers." (PMID 36330448, 2022). "Considering some studies proposing the potential role of opioid signaling axis in cancer, the results can be utilized for understanding the molecular basis of the KRAS mutation-induced tumorigenesis." (PMID 35562390, 2022). "The presence of KRAS mutation is generally associated with clinical aggressiveness of cancer and reduced survival of the patient." (PMID 35340619, 2022). "collected data from KRAS-mutated patients (n=198) from the Cheshire and Merseyside Cancer Network and compared clinical outcomes with a cohort of WT CRC patients." (PMID 36523988, 2022). "Regarding the variability in the mutated position, a well-established example is that approximately 90% of the KRAS mutations occur at codon 12 in cancer." (PMID 35563733, 2022). "Each KRAS mutation subtype has its unique biochemical and clinicopathological features, and the differences between the mutation subtypes in cancer and treatment are not fully understood yet." (PMID 36230855, 2022). "The pivotal hub genes (mainly PPARG, PTGS2, PTPRC, CDKN2A, and PRKACB) and lncRNAs (e.g., OGFRL1, DGCR5, and LINC01842) have been previously reported to have critical roles in the tumorigenesis of many cancers harboring KRAS mutation." (PMID 35562390, 2022). "SOS1 is a promising target in KRAS-mutated cancers as it plays a central role in feedback MAPK reactivation." (PMID 35251972, 2022). "Several other compounds were subsequently discovered and reported to have activity against cancer cells with KRAS G12C mutations." (PMID 36531078, 2022). "A KRAS-dependent pro-inflammatory transcriptome was prominent in human cancers with high KRAS mutation prevalence and poor predicted survival." (PMID 35327394, 2022). "Mutations in the RAS family, mainly in the KRAS isoform, are responsible for some of the deadliest cancers, which has made this protein a major target in biomedical research." (PMID 36697641, 2022). "Since MYC and KRAS are often mutated and constitutively expressed in cancer cells, they can be used as therapeutic targets." (PMID 35328482, 2022). "KRAS mutations, which are one of the most promising and yet unresolved clinical observations in KRAS onco-biology, vary between human cancers in line with the positions and types of substitution of the mutations." (PMID 35563733, 2022). "KRAS mutations lead to abnormal cell proliferation and oncogenic transformation, promote cancer metastasis, and increase the resistance of several cancer types, including CRC, to chemotherapy and epidermal growth factor receptor (EGFR)-targeted therapy." (PMID 36452508, 2022). "A549 cells also exhibit KRAS mutations that induce constitutive activation of the downstream signaling cascade leading to cancer cell proliferation, growth, and survival." (PMID 35928273, 2022). "The importance of this pathway in cancer is highlighted by the fact that KRAS is the most frequently mutated oncogene across cancer types." (PMID 36295658, 2022).
cancer (continued). "This work also suggests that DXI is an interesting lead compound with the potential to treat cancers with oncogenic mutations or expression of KRAS and high levels of DX2, even if further optimization is needed for better efficacy and safety." (PMID 35546148, 2022). "These proteins mediate different signaling pathways that support cancer progression and have been explored for the KRAS mutation dependent genes." (PMID 35785187, 2022). "KRAS-mutated cancers are heterogeneous, and genomic commutations, MET amplification, metabolic reprogramming, and EGFR signaling represent some possible mechanisms of resistance to the KRASG12C inhibitors and immunotherapy." (PMID 36230855, 2022). "Specific mutations in the RAS–RAF–MEK–ERK pathway are associated with 46% of all human cancers, with KRAS mutations in 9% and BRAF mutations in 7% of all human cancers." (PMID 35899070, 2022). "As targeted inhibitors of the MAPK pathway have been approved to treat several types of KRAS-mutated carcinoma, it is worth investigating the therapeutic significance of MAPK inhibitors for patients with MLA." (PMID 35204416, 2022). "KRAS is the most frequently mutated oncogene in cancer, however efforts to develop targeted therapies have been largely unsuccessful." (PMID 33632153, 2021). "We conclude that, at this point in time, despite being such a powerful directed genome editing tool, CRISPR remains to be underutilized for targeting KRAS mutations in cancer." (PMID 34781949, 2021). "Cancer cells bearing distinct KRAS mutations exhibit variable sensitivity to SHP2 inhibitors (SHP2i)." (PMID 34725361, 2021). "Our model system uses overexpression of KRas(G12V), a frequent cancer driver, alone and in combination with PTEN loss to study the response to PTEN loss in a non-tumorigenic and an activated oncogenic background." (PMID 33986306, 2021). "In KRAS-mutated cancer cells, single agent MEK inhibitor treatment is ineffective because it both relieves ERK-dependent negative feedback signaling and induces the expression of RTK and ligands." (PMID 33924994, 2021). "The therapeutic targeting of endogenous TRAIL signaling, thus, opens novel perspectives in the treatment options of KRAS-mutated cancers." (PMID 33791337, 2021). "We performed the xenograft experiment using PATU8902 harboring the KRAS(G12V) mutation, because targeting KRAS(G12V)-driven cancer is an unmet need whereas multiple G12C covalent inhibitors exist that are effective against KRAS(G12C) in xenograft experiments." (PMID 33976200, 2021). "As such, activated RAC1 relays transforming information downstream of over-expressed FAK or mutated KRAS in cancer cells, mainly by binding to and activating its effectors PAK1-3." (PMID 34638434, 2021). "Inhibition of the phosphatase SHP2 exhibits therapeutic potential in cancers dependent on receptor tyrosine kinases and mutated KRAS signaling, as SHP2 plays a critical role in mediating MAPK signaling in cancer cells." (PMID 33446805, 2021). "The presence of KRAS-independent cells is associated with the heterogeneity of KRAS mutant cancers, as well as variable responses to therapies." (PMID 34680229, 2021). "RAS oncogenes (HRAS, NRAS, and KRAS) are one of the most common mutated genes in human cancer with RAS activation occurring in around 30% of all cancers." (PMID 34644109, 2021). "The RAS family member genes, including HRAS, NRAS, and KRAS, are the most frequently mutated oncogenes found in as high as 30% of all human cancers, among which mutations in KRAS constitute 86% of all RAS mutations." (PMID 33668583, 2021). "KRAS activated mutations drive cancer initiation, progression and drug resistance, directly leading to nearly a million deaths per year." (PMID 33562505, 2021). "The trial results suggest GSK-J4 as a potential treatment option for cancer patients with KRAS mutations." (PMID 35004317, 2021).
cancer (continued). "New associations between KRAS and certain cancer phenotypes as well as the development of new agents are providing more hope in the battle against this difficult-to-target oncoprotein." (PMID 33801965, 2021). "The high frequency of KRAS mutations in cancer justifies the multiple efforts invested in developing novel therapeutic strategies targeting KRAS." (PMID 35096591, 2021). "KRAS mutation is generally associated with clinical aggressiveness of cancer and reduced survival of the patients, especially in somatic neoplasm, and in 5% of adult AML." (PMID 33847676, 2021). "While G12 mutations predominate each of these cancers, there are cancer-specific differences in the KRAS mutational spectrum that have functional consequences for therapeutics targeting WT RAS signaling." (PMID 33924994, 2021). "KRAS is the most frequently mutated proto-oncogene in human cancers, and mutated KRAS remains locked in an active state, relaying uncontrolled proliferative signals." (PMID 33917906, 2021). "In general, LIF was found to be overexpressed in human pancreatic carcinomas relative to normal tissue, and that in a pan-cancer analysis LIF was significantly more upregulated in cancers with a mutation in KRAS." (PMID 34395259, 2021). "There is emerging pre-clinical and clinical evidence that BRAF or upstream KRAS mutations in cancer cells results in heightened radiation resistance." (PMID 34537078, 2021). "GSEA revealed a positive enrichment of multiple cancer-associated pathways such as angiogenesis, hypoxia, glycolysis, and KRAS signaling in STAT5cKO BMDMs." (PMID 34743736, 2021). "We demonstrated DEP-isolated CHCs harbored KRAS mutations as a proof of concept, but the overall strategy is applicable to other cancers or diseases with associated cellular biomarkers to provide clinically relevant readouts." (PMID 34561533, 2021). "It has been reported that cancer cells with high NRF2 activation due to KEAP1/NRF2 mutation or KRAS activation depend upon serine and asparagine synthesis pathways for rapid proliferation and survival." (PMID 34247201, 2021). "In fact, it has been observed that FBXW7 mutations in advanced cancers are rarely isolated and frequently occur in concomitance with KRAS mutations especially in advanced CRC." (PMID 33953347, 2021). "Elevated TBK1 activity has implicated in the development of several cancers and elevated expression is associated with KRAS mutations and poor prognosis in PDAC." (PMID 34572737, 2021). "Experimental targeting of EGFR‐BRAF‐MEK in cancer organoids affected signaling and gene expression contingent on predictive KRAS/BRAF mutations and induced cell plasticity overriding default developmental trajectories." (PMID 34409732, 2021). "Data combined from this study and others investigating DNA repair in RAS genes suggests that increased adduct formation and relatively poor repair renders KRAS codon 12 more likely to end up mutated leading to a higher KRAS mutation rate observed in cancers." (PMID 34521464, 2021). "The lower than expected rate of KRAS mutations also highlights that there are few high-frequency mutations in human cancer when one looks across all cancer cases." (PMID 34645806, 2021). "Intensive efforts in finding a way to irreversibly silence KRAS mutations are yet to result in a valid therapy in various cancer forms with high public health burdens, including lung, colorectal and pancreas as reviewed here." (PMID 34781949, 2021).
cancer (continued). "The selective action of high levels of vitamin C on cultured cancer cells harboring KRAS or BRAF mutations has been demonstrated for the first time in colon cancer, which commonly harbors these genetic mutations." (PMID 34065197, 2021). "Several studies have found that the WT allele corresponding to the specific mutated RAS gene (WT HRAS in HRAS-mutated cancers; WT NRAS in NRAS-mutated cancers; WT KRAS in KRAS-mutated cancers) suppresses tumorigenesis." (PMID 33924994, 2021). "Understanding the heterogeneous properties of the KRAS alleles is essential to effectively treating KRAS-driven cancers." (PMID 33753749, 2021). "Recent studies have linked the complexity of YAP/TAZ in cancer with other cancer-relevant factors and pathways, such as KRAS, APC, LKB1, aberrant GPCR signaling, and WNT signaling." (PMID 33830081, 2021). "Our findings on the proportion of all cancers with a RAS gene mutation are consistent with a recent analysis that performed a simpler weighted analysis of KRAS, NRAS, and HRAS mutations." (PMID 34645806, 2021). "Somatic KRAS mutations are prevalent in many cancers, such as colorectal and pancreatic cancer, and leukaemia." (PMID 32948832, 2021). "The RAS gene family is mutated in approximately 30% of human cancers, with the KRAS isoform mutations being the major contributor." (PMID 34944853, 2021). "KRas–the predominantly Ras isoform mutated in cancer–presents a different amino acid in front of the binding pocket (glutamine instead of histidine in position 95) and a more disordered Switch II region even in the active conformation when compared to HRas." (PMID 33681292, 2021). "Mutations in KRAS, an oncogene, are frequent in different kinds of cancers and contribute to tumorigenesis and disease progression." (PMID 35959968, 2021). "Survival tree for cluster 3 featured TMB, BRAF and KRAS mutation status and cancer stage as predictors." (PMID 34600575, 2021). "Genetic alterations that aberrantly activate this kinase pathway in cancers are typically the result of BRAF or KRAS mutations in the majority of cancers displaying MAPK activation." (PMID 34046359, 2021). "KRAS is one of the most frequently mutated genes in human cancer with the G12X (X = V, S, D, A, C) substitution accounting for most of the mutations found in this position." (PMID 33875134, 2021). "Once the KRAS mutations occur, the KRAS activation signaling will be sustained for over 10 years in the somatic evolution of adult cancers." (PMID 33982211, 2021). "The results showed that many cancer proliferation pathways were enriched in the high-risk group, such as angiogenesis-related pathways and the KRAS pathway." (PMID 35154072, 2021). "KRAS mutations are the most common in solid cancers, such as pancreatic cancer, colorectal cancer and, lung cancer, and in these cancers, the mutations affect G12." (PMID 34257597, 2021). "Additional test has revealed that other premalignant lesions or in situ carcinoma are KRAS G12D mutation positive." (PMID 33593396, 2021). "In particular, it has been reported that RTK–SOS2–WT RAS signaling, but not allosteric SOS2 activation, is a critical mediator of mutant KRAS-driven transformation by protecting KRAS-mutated cancer cells from anoikis." (PMID 34205562, 2021). "KRAS mutations are found in 90% of pancreatic ductal adenocarcinomas (PDACs) and are known to be an initiating event for this aggressive cancer type." (PMID 33801965, 2021). "Approximately 30% of human cancers harbour Kirsten Rat Sarcoma Oncogene Homolog (KRAS) gene mutations, and it is one of the most prevalent alterations." (PMID 34944952, 2021). "Cancer-causing mutations in KRAS drastically impair the GTPase activity, resulting in KRAS proteins that are locked in the active GTP-bound conformation, regardless of the upstream signal." (PMID 35004317, 2021).